PIN1 (peptidylprolyl cis/trans isomerase, NIMA-interacting 1)
Diseases named in the same sentence as PIN1 in open-access papers (continued):
Sharing a sentence is not in itself a finding about the gene and the disease.
cancer (continued). "On the contrary, the PIN1 rs2233678 (−842G>C) promoter polymorphism is associated to a reduced expression of the gene and a reduced risk of cancer." (PMID 30873382, 2019). "PIN1 is overexpressed or hyperactivated in many types of cancers and its loss or inactivation blocks tumor growth." (PMID 30873382, 2019). "Here, we review the role of PIN1 in cancer and the regulation of PIN1 expression, and catalog the single nucleotide polymorphisms, and mutations in PIN1 gene associated with cancer." (PMID 30723410, 2018). "Pin1 is highly expressed in the majority of cancers and its deficiency significantly suppresses cancer progression." (PMID 30158600, 2018). "Since the discovery of Pin1 as a key protein in cell cycle regulation, it has been implicated in numerous diseases, ranging from cancer to neurodegenerative diseases." (PMID 30460195, 2018). "PIN1 is overexpressed in various cancer types and is associated with a malignant phenotype and tumor progression." (PMID 30723410, 2018). "Several additional mechanisms are believed to underlie the involvement of PIN1 in the development of multiple cancers, including the regulation of numerous transcription factors responsive to growth-inducing signals." (PMID 30314361, 2018). "PIN1 and other PPIases are overexpressed in many types of cancer and have been implicated in various oncogenic processes." (PMID 30314361, 2018). "This review summarizes the role of PIN1 in cancer and the regulation of PIN1 expression, and is an exhaustive guide to PIN1 SNPs and mutations across cancers." (PMID 30723410, 2018). "Henceforth, in this review, we will be looking at the progress made in understanding the function of Pin1, and how these understandings can aid us in overcoming the diseases implicated by Pin1 such as cancer during drug development." (PMID 30460195, 2018). "Carriers of the −842C variant in the PIN1 promoter have low PIN1 protein levels and low risk for developing cancer." (PMID 30723410, 2018). "Due to its diverse role, perturbation to Pin1 expression levels has been implicated in many diseases such as cancer, and neurodegenerative diseases like Parkinson's and Alzheimer's disease." (PMID 30460195, 2018). "Increased PIN1 expression is usually associated with poorer cancer patient prognosis when compared to non-PIN1 overexpressors." (PMID 30314361, 2018). "Pin1 is hyperactivated in most human cancers and correlates with poor clinical outcome, whereas humans with genetic polymorphisms that reduce PIN1 expression have a lower risk for multiple cancers." (PMID 30093655, 2018). "In this article, the essential role of PIN1 in cell cycle regulation, the mechanisms underlying deregulated PIN1 expression in cancer, and the therapeutic potential of PIN1 inhibitors in cancer therapy were discussed." (PMID 30534074, 2018). "Several studies showed that some single nucleotide polymorphisms (SNPs) in PIN1 gene increase the risk of cancer whereas other variants operate as protective factors." (PMID 30723410, 2018). "A few studies have been reported to determine the association between cancer risk and PIN1 haplotypes." (PMID 28676695, 2017). "Taken together, these results provide a rationale for developing longer half-life ATRA or more potent and specific Pin1-targeted ATRA variants to overcome drug resistance in cancer therapy, especially in combination with sorafenib for HCC." (PMID 28404959, 2017). "Recent study demonstrates that overexpression of PIN1 enhances cancer growth and aggressiveness in EBV-associated NPC17." (PMID 28676695, 2017). "In contrast, genetic single nucleotide polymorphism that reduces Pin1 expression is associated with reduced cancer risk for numerous cancers." (PMID 28383568, 2017). "The present meta-analysis, which included 4,524 cases and 4,561 controls from seven case-control studies, evaluated the association between the PIN1 promoter polymorphism (−842 G>C) and cancer risk." (PMID 25120724, 2014).
cancer (continued). "The results indicated that the PIN1 promoter polymorphism (−842 G>C; rs2233678) contributes to a decreased risk of cancer via attenuating the transcriptional activity." (PMID 25120724, 2014). "High Pin1 expression was associated with higher primary tumor stage (p = 0.035) and overall cancer stage (p = 0.047)." (PMID 25160749, 2014). "A total of seven articles in English regarding the PIN1 promoter polymorphism (−842 G>C) and cancer risk were available for the present meta-analysis." (PMID 25120724, 2014). "Peptidyl-prolylcis-trans isomerase NIMA-interacting 1 (encoded by the PIN1 gene) regulates the conformation of proline-directed phosphorylation sites and is important in the etiology of cancer." (PMID 25120724, 2014). "By immunohistochemistry, we identified that high Pin1 expression was associated with higher primary tumor stage (p = 0.035), higher overall cancer stage (p = 0.047) and poor overall survival (p < 0.001)." (PMID 25160749, 2014). "Since the identification of a functional polymorphism of PIN1, (−842 G>C; rs2233678), in the PIN1 promoter region, numerous studies have evaluated the association between the PIN1 promoter polymorphism (−842 G>C) and cancer risk." (PMID 25120724, 2014). "The relationship between PIN1 −842G/C (rs2233678) polymorphism and cancer risk was inconclusive according to published literature." (PMID 24013949, 2013). "Single nucleotide polymorphisms (SNPs) of PIN1 and cancer risk have been investigated by several studies." (PMID 23874525, 2013). "To confirm the association between −842(G>C) polymorphisms of PIN1 gene and cancer risk, we performed this meta-analysis by pooling all eligible studies to calculate the estimate of overall cancer risk and evaluate influence of cancer types and ethnicity." (PMID 24013949, 2013). "In the present meta-analysis of 10 case-control studies, including 4619 cancer cases and 4661 controls, a significant association was found between PIN1 −842G/C polymorphism and reduced cancer risk under the heterozygous and dominant genetic models." (PMID 24013949, 2013). "Recently, data from a meta-analysis showed that neither the −667T>C nor −842G>C polymorphism was associated with susceptibility to Alzihamer's disease; however, the correlation between PIN1 polymorphisms and cancer risk is still inconclusive." (PMID 23976970, 2013). "In conclusion, this meta-analysis suggests that the −842G/C polymorphism in PIN1 gene is associated with a significantly reduced risk of cancer, especially in Asian populations." (PMID 24013949, 2013). "Taken together, these results revealed that −842G/C polymorphisms in the PIN1 promoter region was only associated with an increased risk of cancer in Asians." (PMID 24013949, 2013). "We demonstrated that the rs2233678 (−842 G>C) polymorphism in the PIN1 promoter region was associated with a significantly decreased susceptibility to cancer." (PMID 23874525, 2013). "The −667T>C and −842G>C polymorphisms occur in PIN1 promoter region, and they have been suspected as risk factors of cancer and Alzihamer's disease." (PMID 23976970, 2013). "Pin1 is also implicated in diseases such as cancer and Alzheimer's disease and is a potential therapeutic target." (PMID 23407864, 2013). "The two single nucleotide polymorphisms (−677T>C, −842G>C) in the PIN1 promoter region have been suspected of being associated with cancer risk for years, but the conclusion is still inconclusive." (PMID 23976970, 2013). "This meta-analysis suggests that the PIN1 −842G/C polymorphism is associated with a significantly reduced risk of cancer, especially in Asian populations." (PMID 24013949, 2013). "Overall, a significant association exists between −842G/C polymorphisms in the PIN1 promoter region and cancer risk." (PMID 24013949, 2013). "During sub-group analyses, we found that control source also affected the association between −842G/C polymorphisms in the PIN1 promoter region and cancer risk." (PMID 24013949, 2013).
cancer (continued). "In the sub-group analyses of squamous cancer, and other cancers, we did find any significant association between −842G/C polymorphisms in the PIN1 promoter region and cancer risk." (PMID 24013949, 2013). "Because of its significant role in cell cycle regulation by a unique mechanism, Pin1 represents an intriguing diagnostic and therapeutic target for cancer." (PMID 23028504, 2012). "Previous studies have demonstrated that PIN1 plays a crucial role in multiple cellular processes and, likewise, it has been implicated in pathogenesis of several diseases, including cancer, inflammation to neurodegenerative diseases." (PMID 19909517, 2009). "Pin1 has been shown to play a major role in modulating protein function, and its overexpression is implicated in the onset and progression of several cancers, activating several oncoproteins, such as those in the KRAS pathway, while simultaneously inactivating tumor suppressors." (PMID 41322199, 2025). "Furthermore, the presence of Pin1 in cancer patients has been demonstrated to be associated with disease severity and poor clinical outcomes." (PMID 39624096, 2024). "Importantly, PIN1 expression level is highly upregulated in most cancer cells and is associated with malignant features and therefore poor outcomes." (PMID 39202474, 2024). "Notably, in addition to its function as a proline isomerase, in recent years there has been a growing interest in the role of Pin1 in modulating cell death, functionality, and mutations in different cancers." (PMID 39624096, 2024). "Consequently, BRCAness (similar to BRCA1 or BRCA2 gene mutation signatures) in cancer cells has been established to be associated with the inactivation of Pin1, which is essential for PARP inhibitor treatment, as it sensitizes cells." (PMID 39624096, 2024). "Dysregulation of Pin1 has been implicated in various pathological conditions, particularly cancer." (PMID 38318109, 2024). "The association between survival profile and Pin1 expression in two other forms of cancer is unknown." (PMID 37511442, 2023). "However, only two cancer types, renal and pancreatic, are Pin1 expression prognostic: high Pin1 expression is associated with a better prognosis, according to the Human Protein Atlas." (PMID 37511442, 2023). "However, Pin1 is a well-known oncogene, and overexpression of Pin1 has been reported to be associated with several cancers." (PMID 36304997, 2022). "This Pin1-dependent isomerization leads to changes in function and thus the conformation, of many key proteins, which play key roles in many signaling pathways implicated in cancer, including β-catenin, ER-α, NFκB, Stat3, cyclin D1, Notch, and AKT." (PMID 35450041, 2022). "Impaired Pin1 activity has been implicated in pathogenesis of both cancer and AD." (PMID 34523079, 2021). "In fact, PIN1 overexpression may be an essential cause for the tumorigenesis and cancer stemness development in breast and pancreatic carcinomas." (PMID 32268506, 2020). "Finally, ATRA -and to a lesser extend ATO- were proposed to inhibit Pin-1, an enzyme implicated in the progression of multiple cancer types." (PMID 32295268, 2020). "Increasing evidence has illustrated that Pin1 is involved in cancer-associated angiogenesis." (PMID 32296699, 2020). "Indeed, in spite of a very low mutation frequency of the PIN1 gene, in human cancers PIN1 is prevalently overexpressed." (PMID 30873382, 2019).
cancer (continued). "Thus, it is very likely that the high expression of ACC1 protein in cancer cells is caused by two independent mechanisms; at the transcriptional level and at the Pin1-mediated posttranscriptional-level." (PMID 30899433, 2019). "As a consequence, subtle alterations of PIN1 expression or activity or of the phosphorylation status of its targets have been linked to a number of pathologies, ranging from inflammation to neurodegeneration and cancer." (PMID 30873382, 2019). "However, the interested reader is referred to an excellent review on single nucleotide polymorphisms and mutations of Pin1 in cancers." (PMID 31861908, 2019). "So far, 32 somatic mutations in PIN1 gene have been found in different types of cancer." (PMID 30723410, 2018). "Several SNPs, located in the promoter or coding region of PIN1, are associated with cancer risk." (PMID 30723410, 2018). "Follow-up studies showed that Pin1 expression is associated with poor cancer prognosis." (PMID 30442923, 2018). "Several mechanisms have been implicated in aberrant PIN1 expression/activity in cancer." (PMID 30314361, 2018). "Although further studies are required, we believe that investigating the complex pattern of PIN1 gene alterations and their effects on PIN1 protein structure and function is a valid strategy for identifying new biomarkers for susceptibility to cancer and response to anti-PIN1 inhibitors." (PMID 30723410, 2018). "Given the importance of PIN1 in cell cycle progression, it is expected that PIN1 may be implicated in cancer development." (PMID 30534074, 2018). "Some SNPs in PIN1 gene were found to associate with cancer risk." (PMID 30723410, 2018). "Little has been reported so far about PIN1 somatic mutations and cancer." (PMID 30723410, 2018). "As a consequence of this function, PIN1 inhibition causes the collapse of numerous oncogenic pathways at the same time, making this isomerase an attractive drug target for the development of treatments against aggressive and drug-resistant cancers." (PMID 28598431, 2017). "Most of all, however, KPT-6566 represents a one of a kind PIN1 inhibitor because it associates a highly specific PIN1 inhibitory activity with the release of a reactive quinone-mimicking byproduct that acts downstream of PIN1 and generates DNA damage and elicits cancer cell death." (PMID 28598431, 2017). "The Pin1 gene (Peptidyl-prolyl cis–trans isomerase NIMA-interacting 1) has demonstrated certain functional polymorphisms associated with cancer risk; the gene regulates conformation of phosphorylation sites, and it has been involved in multiple oncogenic signaling pathways as a critical catalyst." (PMID 28538688, 2017). "Notably, we consistently observed that KPT-6566 treatment of MEFs and human cancer cells caused a decrease of endogenous PIN1 levels." (PMID 28598431, 2017). "Pin1-mediated fatty acid accumulation may be linked to cancer progression because cancer cells require an energy source for proliferation." (PMID 27618008, 2016). "Investigations of the gene-environmental interaction may give us a better understanding of the roles of Pin1 polymorphisms in human cancers." (PMID 27029791, 2016). "In conclusion, the present meta-analysis provides clear evidence that the PIN1 promoter polymorphism (−842 G>C) contributes to a decreased cancer risk, supporting the hypothesis that the polymorphism may present as a biomarker for susceptibility to cancer." (PMID 25120724, 2014). "Recent studies have investigated the association between the PIN1 promoter polymorphism (−842 G>C) and the risk of cancer in various organs, including the liver, lungs and breast, squamous cell carcinoma of the head and neck, and nasopharyngeal and esophageal cancer." (PMID 25120724, 2014). "Therefore, the results of the present study must be interpreted with caution and large-scale, detailed and mechanistic studies are required to support the association between the PIN1 promoter polymorphism (−842 G>C) and decreased cancer risk." (PMID 25120724, 2014).
cancer (continued). "Furthermore, only three studies included European individuals, therefore, larger-scale studies and combined analysis are required to further support the association between the PIN1 promoter polymorphism (−842 G>C) and decreased cancer risk." (PMID 25120724, 2014). "Functional studies of the PIN1 promoter polymorphism (−842 G>C) further support the results of the present study, whereby individuals with variant GC and GC/CC genotypes were significantly associated with a decreased risk of cancer." (PMID 25120724, 2014). "Interestingly, Pin1 deregulation is implicated in a number of conditions, notably ageing and age-related diseases, including cancer and AD." (PMID 24877062, 2014). "Additionally, studies suggest that single nucleotide polymorphisms (SNPs) of PIN1 are associated with Alzheimer's disease and cancer." (PMID 23976970, 2013). "Association of PIN1 polymorphisms with cancer risk estimated with raw data." (PMID 23976970, 2013). "Considering the oncogenetic role of PIN1 and the altered promoter activity caused by −842 G>C variation, it is reasonable to conclude that the −842 G>C polymorphism in the PIN1 promoter region may alter cancer risk." (PMID 23874525, 2013). "Second, the sample size of the included studies was not large enough, which could decrease the statistical power to better evaluate the association between −842G/C polymorphism in the PIN1 promoter region and cancer risk." (PMID 24013949, 2013). "Stratified analyses of the −842G/C Polymorphisms in PIN1 Gene with cancer risk." (PMID 24013949, 2013). "Association of PIN1 polymorphisms with cancer risk estimated with adjusted ORs and 95% CIs." (PMID 23976970, 2013). "Published evidence suggests that the rs2233678 (−842 G>C) polymorphism in the PIN1 (peptidyl-prolyl cis/trans somerase NIMA-interacting 1) promoter region may be associated with cancer risk; however, the conclusion is still inconclusive." (PMID 23874525, 2013). "The present meta-analysis was designed to ascertain whether the two common SNPs (−667T>C, −842G>C) of PIN1 are associated with cancer risk and evaluate the impact of ethnicities." (PMID 23976970, 2013). "Combined with the oncogenetic role of PIN1, this may explain why the −842C allele reduced cancer risk." (PMID 23976970, 2013). "To determine whether the biological functions affected by PIN1 knockdown are also linked to known BPs in cancer, we performed a functional enrichment analysis with the MoonlighR package, which enriches known BPs in different cancer types based on differentially regulated genes." (PMID 38216124, 2024). "Similarly, another report claimed that PIN1 may serve as a viable therapeutic target of LSCC because it is not only highly expressed in LSCC but also linked to the risk of developing cancer." (PMID 37105032, 2023). "Notably, Pin1 deregulation is implicated in age-dependent human diseases, including cancer and AD." (PMID 32500074, 2020). "Furthermore, the mechanisms underlying PIN1 overexpression in cancers were also explored." (PMID 30534074, 2018). "Finally, investigations of the gene-environment interaction may lead to an improved, more comprehensive understanding of the roles of PIN1 polymorphisms in the etiology of cancer." (PMID 25120724, 2014). "Therefore, the −842 C variant genotype may lead to a reduced expression of PIN1 and may be associated with a reduced risk of cancer." (PMID 25120724, 2014). "Notably, Pin1 overexpression is associated with poor clinical outcomes in human cancer patients." (PMID 24899581, 2014). "Thus, it is biologically possible that the functional polymorphisms of PIN1 may be important in the etiology of cancer." (PMID 25120724, 2014). "PIN1 degradation was assessed by Western blotting in multiple cancer cell lines, and further investigated through a series of computational and mechanistic experiments." (PMID 41900774, 2026).